ZBTB9 (zinc finger and BTB domain containing 9)
Description:
May be involved in transcriptional regulation.
Synonyms: MGC23166; ZNF919
Tractability: PROTAC: UniProt records ubiquitination sites on it; ubiquitination databases record sites on it; its protein half-life has been measured.
Target class: Transcription factor
Gene: Protein-coding gene on chromosome 6 (33,453,970 to 33,457,544, forward strand). Ensembl gene ENSG00000213588.
Subcellular location: Nucleus
Subcellular location (Human Protein Atlas): Nucleoplasm; Cytosol; Nuclear membrane
Gene Ontology:
Molecular function: identical protein binding; protein binding; DNA-binding transcription factor activity, RNA polymerase II-specific; RNA polymerase II cis-regulatory region sequence-specific DNA binding
Biological process: regulation of transcription by RNA polymerase II
Cellular component: nucleus
Genetic constraint (gnomAD): Loss-of-function variants: 17 observed, 27.49 expected, observed/expected ratio (o/e) 0.62, 90% interval 0.42 to 0.93. The upper end of that interval is the gene's LOEUF score, 0.93, which puts it in group 3 of 6, group 1 being the genes least tolerant of losing a copy. Missense variants: 470 observed, 580.93 expected, observed/expected ratio (o/e) 0.81, 90% interval 0.75 to 0.87. Synonymous variants: 210 observed, 227.93 expected, observed/expected ratio (o/e) 0.92, 90% interval 0.82 to 1.03.
Homologues: Orthologues: chimpanzee ZBTB9 (99% identical), macaque ZBTB9 (99% identical), guinea pig ZBTB9 (86% identical), pig ZBTB9 (86% identical), rabbit ZBTB9 (83% identical), dog ZBTB9 (82% identical), rat Zbtb9 (76% identical), mouse Zbtb9 (76% identical), tropical clawed frog zbtb9 (45% identical). Paralogues in human: ZBTB22 (36% identical), ZBTB8B (19% identical), ZBTB10 (18% identical), ZBTB8A (16% identical), C17orf113 (12% identical).
Diseases named in the same sentence as ZBTB9 in open-access papers:
ZBTB9 is named in the same sentence as 4 diseases in open-access papers, as found by Europe PMC text mining. Sharing a sentence is not in itself a finding about the gene and the disease. The quoted sentences say what the papers report.
Obesity (1 paper, 2024). Accumulation of substantial excess body fat. "We now report for the first time that ZBTB9 regulates adipogenesis and adipocyte function, suggesting a possible molecular mechanism underlying the altered risk of obesity and T2D associated with allelic variation near ZBTB9." (PMID 39542250, 2024). "Our findings reveal cell-state dependent roles of ZBTB9 in adipocytes, identifying a new molecule that regulates adipocyte biology as both a positive and negative regulator of PPARγ signaling depending on the cellular context, and thus may be important in the pathogenesis of obesity and T2D." (PMID 39542250, 2024).
tumor (2 papers, 2021 to 2022). "The correlations between ZBTB9 expression levels and different clinical characteristics were analyzed via the UALCAN database, which indicated that higher ZBTB9 expression was significantly associated with higher individual stages and tumor grade." (PMID 36522647, 2022). "To further confirm these findings, we conducted ZBTB9 IHC between the tumor and paired adjacent normal tissues, results also demonstrated that ZBTB9 protein was significantly higher in tumor samples." (PMID 36522647, 2022). "After the knockdown of ZBTB9, evidently inhibited capacities of tumor cells proliferation and migration were observed." (PMID 36522647, 2022). "Then based on GSE76427 and GSE36376 of GEO database, evident upregulation of ZBTB9 was also detected in LIHC tumor tissues compared to normal tissues." (PMID 36522647, 2022). "However, in tumor initiation and progression, the role of ZBTB9, one of the protein family, and its prognostic value were yet to be elucidated in Liver Hepatocellular Carcinoma (LIHC)." (PMID 36522647, 2022). "In addition, the levels of ZBTB9 showed the relation with higher tumor grade and individual stages for LIHC patients." (PMID 36522647, 2022). "Which confirmed the promotive role of ZBTB9 in tumor cell development." (PMID 36522647, 2022). "According to the results of agarose gel electrophoresis, it was obvious that in most samples, the promoter methylations of ZBTB9 were significantly lower in tumor samples than paired adjacent normal tissues (P = 0.033) (the odd labels are adjacent normal tissues and even labels are tumor tissues)." (PMID 36522647, 2022). "Promoter methylation analysis was conducted via UALCAN, and we analyzed the ZBTB9 methylation levels, which showed that the promoter methylation level of ZBTB9 in LIHC tumor tissues was significantly lower than that in adjacent normal tissues." (PMID 36522647, 2022). "ZBTB9 is a member of ZBTB proteins, and the relationship between its expression and tumor development is poorly studied." (PMID 36522647, 2022). "ZBTB9 was identified as a novel biomarker to predict the prognosis and tumor progression in LIHC, and a promising therapeutic target to invert tumor development." (PMID 36522647, 2022). "Further GSEA analysis showed that in high ZBTB9 expression samples, the G2M checkpoint, epithelial-mesenchymal transition, E2F targets, and KRAS-related signaling pathways were significantly activated, which has been reported to participate in tumor proliferation and progression." (PMID 36522647, 2022).
cancer (1 paper, 2022). A tumor composed of atypical neoplastic, often pleomorphic cells that invade other tissues. "We further explored the specific mutation type and site of ZBTB9 among cancers." (PMID 36522647, 2022). "In addition, the Cox regression analysis based on pan-cancer data also demonstrated that ZBTB9 was a notable risk factor in many cancers, including LIHC." (PMID 36522647, 2022).
metabolic disease (1 paper, 2024). A congenital disorder (due to inherited enzyme abnormality) or acquired (due to failure of a metabolically important organ) disorder resulting from an abnormal metabolic process. "Little is known about the cellular function of ZBTB9, although multiple GWAS suggested a role in metabolic disease susceptibility." (PMID 39542250, 2024).